LEP (leptin)
Diseases named in the same sentence as LEP in open-access papers (continued):
Sharing a sentence is not in itself a finding about the gene and the disease.
infarction (9 papers, 2012 to 2024). A localised pathological necrosis of tissue resulting from obstruction of the blood supply usually by a thrombus, an embolus, or vascular torsion. "Our findings highlight the importance of PEG in facilitating the transport of the leptin-PEG-FBP peptide through the cerebrospinal fluid to the infarction area, as supported by the biodistribution data." (PMID 38203830, 2024). "Our results are consistent with previous studies revealing that leptin may exert its neuroprotective effects by reducing the infarct size, improving neurological function scores and reducing brain edema." (PMID 30632310, 2019). "This is confirmed by the elevated concentrations of LEP within the first 24 hours of infarction." (PMID 26389928, 2015). "In the present study, a comparable decrease in leptin was observed in the SG and RYGB groups; notwithstanding, in the IT group, in which a significant decrease in the infarction size was not obtained, the decrease in leptin (by 22%) was not significant." (PMID 34903800, 2021).
invasive breast carcinoma (9 papers, 2009 to 2024). A carcinoma that infiltrates the breast parenchyma. "AQP1 was positively correlation with leptin in invasive breast carcinoma, showing that leptin is associated with AQP1." (PMID 38791252, 2024). "AQP1 showed a high positive Spearman correlation coefficient (0.503) among the genes co-expressed with leptin in invasive breast carcinoma." (PMID 38791252, 2024). "This study is designed to investigate the prognostic value of the pre- and post-treatment serum levels of adiponectin and leptin in luminal A and B invasive breast cancer (IBrC) patients based on six-years follow-up." (PMID 36556428, 2022). "levels of leptin in cases with invasive breast cancer, patients with carcinoma in situ and control subjects were 10.4(±7.0), 8.7(±5.3) and 8.4 (±5.3 ng ml−1), respectively." (PMID 19223908, 2009). "Together, this suggests that invasive breast carcinoma overexpresses leptin compared to normal breast tissue and that leptin levels may also be a potential prognostic factor for ER+/PR+ invasive breast carcinomas." (PMID 24176089, 2013). "Baseline data from a randomized controlled trial, in which premenopausal women with intraepithelial neoplasia or micro-invasive breast cancer were compared to healthy high-risk women (5-year Gail score > 1.3%), showed a decrease in risk with increasing adiponectin (but not leptin) concentrations." (PMID 35948877, 2022).
Miscarriage (9 papers, 2016 to 2024). A pregnancy that ends at a stage in which the fetus is incapable of surviving on its own, defined as the spontaneous loss of a fetus before the 22th week of pregnancy. "It was thought that the impairment of leptin balance and the resulting leptin resistance may be associated with poor reproductive performance and miscarriage." (PMID 34262401, 2021). "First, the association between increased BMI and increased risk of miscarriage might be related to the action of leptin produced in the adipose tissue." (PMID 34220704, 2021). "High levels of leptin protein have also been found in deciduas from miscarriages, as well as in placentas from hydatidiform mole." (PMID 39090270, 2024). "Both low concentrations of leptin and leptin resistance may play a role in miscarriage because this hormone has a role in embryonic implantation and the establishment of the placenta." (PMID 35239212, 2022). "On the other hand, SNPs of leptin and LEPR genes are risk factors for miscarriage." (PMID 29160594, 2018).
myocardial ischemia (9 papers, 2010 to 2025). A disorder of cardiac function caused by insufficient blood flow to the muscle tissue of the heart. "Our results indicate that all cardioplegic solutions reduce leptin levels following I/R, particularly in cases of prolonged myocardial ischemia." (PMID 40729334, 2025). "The severity of myocardial ischemia and the magnitude of reperfusion injury relate most likely to “time to reperfusion,” which in turn correlates with cardiac leptin synthesis." (PMID 30312306, 2018). "In summary, we demonstrated that overexpressed cardiac leptin, coinciding with myocardial ischemia and reperfusion, potentiates myocardial remodeling." (PMID 30312306, 2018). "The upregulation of IL-6 and the increase in its signaling product hs-CRP suggests the possible involvement of leptin in the signaling cascade through activation of leptin receptor after myocardial ischemia." (PMID 22891684, 2012). "Acute MI induces leptin expression in the heart, however the role of myocardial leptin in cardiac ischemia and reperfusion (IR) remains unknown." (PMID 30312306, 2018). "We hypothesise that the increase in values of IL-6, hs-CRP and their correlation to leptin in AMI patients could be due to participation of leptin in the signaling cascade after myocardial ischemia." (PMID 22891684, 2012).
pulmonary tuberculosis (9 papers, 2007 to 2024). A bacterial infection that affects the lungs and is caused by Mycobacterium tuberculosis. "Splenic infection of the diet-D fed animals might have accelerated the maturation of double positive T-cells inclined towards CD4+63 rather than CD8+ and could explain increased CD4+/CD8+ T cells ratio, something also found to be correlated with pulmonary tuberculosis in leptin-deficient mice." (PMID 29116252, 2017). "Clinical research has demonstrated that pulmonary tuberculosis is characterized by diminished circulating adiponectin and leptin levels, as well as augmented resistin levels." (PMID 38263093, 2024). "The patients with pulmonary tuberculosis (PTB) have decreased serum leptin levels, and an increase in adiponectin may serve as a reliable biomarker for predicting the development and progression of PTB pathogenesis." (PMID 30534129, 2018). "The relationship between leptin and pulmonary tuberculosis is notcompletely understood." (PMID 17497033, 2007). "However, the reduction of leptin levels may represent a protective component of the immune response in pulmonary TB." (PMID 21040518, 2010). "The previous findings are not replicated in two studies, which report higher leptin concentrations in patients with active pulmonary TB versus controls." (PMID 21040518, 2010).
reflux esophagitis (9 papers, 2008 to 2023). "Interestingly, abdominal visceral fat and leptin, independently of each other, increased the risk of reflux esophagitis." (PMID 35409299, 2022). "According to Nam’s study, visceral fat, leptin as well as circulating levels of IL-1 beta and IL-6 were higher in patients with reflux esophagitis than healthy controls." (PMID 34793546, 2021). "Additionally, appetite and caloric intake are influenced by factors such as vomiting, gastroesophageal reflux, oral aversion, delayed gastric emptying, nausea, high cytokine levels, renal tubular acidosis and levels of ghrelin and leptin hormone and must be taken into consideration." (PMID 32521626, 2020). "Moreover, Leptin has also been found to have a positive association with reflux esophagitis that was independent of visceral fat." (PMID 26506614, 2015).
relapsing-remitting MS (9 papers, 2013 to 2025). "In human studies, serum leptin levels were found to be increased prior to onset of clinical symptoms in relapsing-remitting MS, indicating that leptin may both contribute to the pathogenesis of MS and be a useful marker of disease." (PMID 33584724, 2020). "In contrast, in acute neuroinflammation [e.g., relapsing remitting MS (RRMS)], leptin-primed microglia enhance antigen presentation and secrete pro-inflammatory cytokines that can activate autoreactive T cells." (PMID 41516046, 2025).
respiratory depression (9 papers, 2012 to 2023). A decrease in ventilation secondary to impaired signals from the central nervous system. "These high leptin levels are related to leptin-resistant and impaired leptin singling in the brain, causing respiratory depression." (PMID 37841315, 2023). "Studies in animal models have shown that leptin is a powerful stimulant of ventilation that can prevent respiratory depression in obese animals." (PMID 34671315, 2021). "The increase in serum leptin levels in patients with OSAS may be a compensatory protective mechanism to prevent respiratory depression." (PMID 34671315, 2021). "Leptin can directly act on the respiratory control center to increase the sensitivity of CO2 during sleep and subsequently prevent respiratory depression in obese subjects." (PMID 35162313, 2022).
thrombosis (9 papers, 2018 to 2025). "This correlation underscores the importance of considering hormonal influences, particularly prolactin and leptin, in the context of thrombosis risk when using antipsychotic medications." (PMID 38255892, 2024). "Thrombosis and inflammation have been associated with increased levels of satiety hormone leptin, commonly observed in patients who are obese who become leptin resistant." (PMID 36250653, 2022). "It has been demonstrated that administration of leptin neutralizing antibodies was associated with protection from lethal venous thrombosis and PE23." (PMID 29720688, 2018). "Moreover, experimental studies in mice have demonstrated that leptin promotes both arterial and venous thrombosis." (PMID 38818568, 2024).
uremia (9 papers, 2015 to 2025). A clinical syndrome associated with the retention of renal waste products or uremic toxins in the blood. "In addition, low intake and/or insufficient absorption of nutrients has been observed in HD patients, which is associated with age, uremia, concomitant pathologies and the alteration of hormones such as leptin and ghrelin." (PMID 37242121, 2023). "Higher circulating leptin and adiponectin levels are observed in uremia due to decreased renal degradation and/or clearance and increased production." (PMID 41295840, 2025). "Recent data have shown that lipopolysaccharides, TNF-α, and IL-1 present in uremia stimulate leptin expression by signaling through the central melanocortin system." (PMID 34835927, 2021). "Leptin production is increased in adipocytes in uremic conditions and in mice, uremia increases resistin expression." (PMID 28333114, 2017). "Severe SHPT inhibited uremia-enhanced leptin production in 3T3-L1 adipocytes, which was attenuated after PTX." (PMID 27307101, 2016).
acute coronary syndrome (8 papers, 2012 to 2025). Signs and symptoms related to acute ischemia of the myocardium secondary to coronary artery disease. "Several studies evaluated the association between adipokines, including leptin, in patients with acute coronary syndrome (ACS)." (PMID 40362168, 2025). "The aim of the present study was to evaluate leptin, pregnancy-associated plasma protein A (PAPP-A) and C-reactive protein (CRP) levels in patients with acute coronary syndrome and to assess their diagnostic efficacy in the identification of vulnerable plaques." (PMID 22836155, 2012). "The aim of our study was to investigate the influence of a two-week cardiac rehabilitation programme on HIF-1A, NfkB and NILCO-dependent leptin and VEGF A cross-talk in patients after acute coronary syndrome." (PMID 35821400, 2022). "A 2-week cardiac rehabilitation programme in patients after acute coronary syndrome increases the serum levels of VEGF A and decreases blood concentrations of leptin." (PMID 35821400, 2022). "This study aimed to investigate the influence of cardiac rehabilitation (CR) on HIF-1A, NfkB and NILCO dependent leptin and VEGF A cross-talk in patients after acute coronary syndrome (ACS)." (PMID 35821400, 2022).
amyloid (8 papers, 2017 to 2025). "In one series of 1036 memory clinic patients in whom both CSF and plasma sampling were undertaken, low plasma leptin was associated with CSF amyloid positivity (Aβ1-42 < 500 pg/mL), especially in those who were both amyloid- and tau-positive." (PMID 41516046, 2025). "Generally, evidence from epidemiology, neuroimaging, and biomarker studies suggests that sustained normal leptin signaling from midlife may reduce AD risk by limiting amyloid and tau pathology, preserving synapses, and reducing neuroinflammation." (PMID 41516046, 2025). "Alternatively, BMI changes might be driven by Aβ accumulation affecting hypothalamic leptin signaling early in the disease process that leads to weight loss and pathologically low leptin state that progressively worsens as the amyloid burden increases." (PMID 28450713, 2017). "JAMA Network data show plasma leptin inversely correlates with amyloid and tau PET load in older adults, yet this protective signal diminishes when leptin resistance confounds central action." (PMID 41155642, 2025). "The presence of amyloid and tau pathology in the hypothalamus supports a bidirectional relationship, where AD pathology disrupts leptin signaling, and impaired leptin signaling, in turn, accelerates AD progression." (PMID 41516046, 2025). "At 9 months, corresponding to early amyloid pathology, leptin levels were elevated in the hippocampus of APP/PS1 mice but unchanged in the neocortex." (PMID 41516046, 2025). "Leptin is a satiety hormone that mediates feeding responses and energy metabolism but has also been found to be neuroprotective against toxic Aβ in-vitro and prevents amyloid plaque build-up in mouse models of AD." (PMID 33218163, 2020). "Although previous studies suggest that amyloid is also capable of attenuating hypothalamic neuron reactivity to leptin and ghrelin, evidence from both mouse models and AD patients suggest that hypothalamic impairment and metabolic abnormalities precede amyloid and tau pathology." (PMID 32993686, 2020). "Ishii and Iadecola (2015) reported low plasma leptin levels in Tg2576 mice with low body weight at 3 months of age, before amyloid plaque formation, with the absence of hyperpolarizing responses to leptin in the hypothalamic neuropeptide Y (NPY)." (PMID 35958733, 2022).
benign prostate hyperplasia (8 papers, 2012 to 2023). "Serum leptin, an adipokine, was also significantly associated with prostate enlargement (p = 0.008)." (PMID 27336586, 2016). "High expression levels of leptin and Ob‐R (class I cytokine‐receptor) have been observed in prostate tumors; leptin was found to be significantly higher in PCa than in benign prostatic hyperplasia (BPH) tissue." (PMID 32573960, 2020). "Overall, greater body mass, estimated by BMI, WHR, WC, %BF, fat mass, and blood leptin, was significantly associated with prostate enlargement but not with LUTS severity." (PMID 27336586, 2016). "It is also known that leptin stimulates cellular proliferation of benign prostatic hyperplasia." (PMID 22654635, 2012). "In our previous study, we were unable to find any differences in leptin levels between PC and benign prostate hyperplasia (BPH) men, however, we found the higher leptin-to-adiponectin ratio in individuals with PC and we demonstrated connections between serum leptin and aggressiveness of PC." (PMID 32326011, 2020).
Brain atrophy (8 papers, 2014 to 2025). Partial or complete wasting (loss) of brain tissue that was once present. "Increased levels of leptin in the bloodstream can increase brain volume and decrease brain atrophy as well as contribute to the formation of synapses and growth of axons associated with neuroprotection." (PMID 37927863, 2023). "One study showed that elderly obese subjects with higher leptin levels showed concomitant greater global brain atrophy, suggesting that brain resistance to its action may develop in obese individuals despite peripheral hyperproduction of leptin." (PMID 26432692, 2016). "Moreover the fact that proliferation and neurogenesis processes, as wells as brain atrophy, are age dependent, support the idea that changes are due to the diabetic process, since leptin signalling alterations are present from the beginning in the db/db mice." (PMID 24586614, 2014).
cardiomyopathy (8 papers, 2013 to 2023). A disease of the heart muscle or myocardium proper. "Administration of adenoviral leptin also improved cardiomyopathy and myocardial steatosis in transgenic mice." (PMID 37189644, 2023). "Obese Leptin resistant (db/db) mice characterized by DM2 were treated with angiotensin II (AT) for 4 weeks to enhance the development of cardiomyopathy." (PMID 30071860, 2018). "However, the role of cardiac leptin signaling in mediating the cardiomyopathy associated with increased body weight is unclear, in particular, whether it develops subsequently to cardiac leptin resistance or overactivation of hypertrophic signaling pathways via elevated leptin levels." (PMID 23841921, 2013).